CLHC1 (clathrin heavy chain linker domain containing 1)
Synonyms: C2orf63; FLJ31438
Tractability: PROTAC: ubiquitination databases record sites on it.
Gene: Protein-coding gene on chromosome 2 (55,172,547 to 55,232,563, reverse strand). Ensembl gene ENSG00000162994.
Subcellular location (Human Protein Atlas): Centrosome; Nucleoli fibrillar center
Gene Ontology:
Molecular function: protein binding
Genetic constraint (gnomAD): Loss-of-function variants: 34 observed, 38.17 expected, observed/expected ratio (o/e) 0.89, 90% interval 0.68 to 1.19. The upper end of that interval is the gene's LOEUF score, 1.19, which puts it in group 5 of 6, group 1 being the genes least tolerant of losing a copy. Missense variants: 481 observed, 439.37 expected, observed/expected ratio (o/e) 1.09, 90% interval 1.01 to 1.18. Synonymous variants: 136 observed, 156.82 expected, observed/expected ratio (o/e) 0.87, 90% interval 0.75 to 1.
Homologues: Orthologues: chimpanzee CLHC1 (99% identical), macaque CLHC1 (95% identical), pig CLHC1 (81% identical), dog CLHC1 (75% identical), mouse Clhc1 (70% identical), rat Clhc1 (70% identical), tropical clawed frog clhc1 (40% identical), Drosophila melanogaster Chc (20% identical), Caenorhabditis elegans chc-1 (20% identical). Paralogues in human: CLTC (22% identical), CLTCL1 (20% identical).
Diseases named in the same sentence as CLHC1 in open-access papers:
CLHC1 is named in the same sentence as 6 diseases in open-access papers, as found by Europe PMC text mining. Sharing a sentence is not in itself a finding about the gene and the disease. The quoted sentences say what the papers report.
bipolar disorder (1 paper, 2025). A disorder of the brain that causes unusual shifts in mood, energy, activity levels and the ability to carry out day-to-day tasks. "Polymorphisms in the human CLHC1 gene have been associated with bipolar disorder, major depressive disorder and brain structure differences." (PMID 41143948, 2025).
lung adenocarcinoma (1 paper, 2022). A carcinoma that arises from the lung and is characterized by the presence of malignant glandular epithelial cells. "In our case, a novel CLHC1/RNT4 intergenic region, ALK fusion, was identified for the first time in a lung adenocarcinoma patient with BM, who benefited from crizotinib and endostar sequential alectinib." (PMID 35446297, 2022).
cancer (1 paper, 2019). A tumor composed of atypical neoplastic, often pleomorphic cells that invade other tissues. "Although many mutations have been identified from CLHC1 in various human cancer types including HBC, their potential roles in cancer are largely unknown and demand further study." (PMID 31842489, 2019).
CLHC1 also shares sentences with these, for which no sentence is quoted: Aortic dissection (1 paper); colorectal cancer (1); major depressive disorder (1).